PARP1 (poly(ADP-ribose) polymerase 1)
Diseases named in the same sentence as PARP1 in open-access papers (continued):
Sharing a sentence is not in itself a finding about the gene and the disease.
melanoma (continued). "Inhibition of PARP1 reduced vasculogenic mimicry in melanoma cells, indicating the potential of PARP1 inhibitors on attenuating tumor metastasis." (PMID 28991194, 2017). "The level of activated (cleaved) caspase 3 and inactivated (cleaved) poly-[ADP ribose]-polymerase-1 (PARP-1) was increased in melanoma cells treated for 72 h with the Les-3833." (PMID 28409496, 2017). "PARP-1 degradation induced by the Les-3833 in human melanoma cells demonstrates an additional mechanism in the biological action of this potential anticancer drug." (PMID 28409496, 2017). "To test the potential anti-melanoma effect of PARP1 inhibitors we established six patient-derived melanoma cell lines." (PMID 27705909, 2016). "PARP1 inhibition caused accumulation of DSBs, which was associated with apoptosis in LIG4 deficient melanoma cells." (PMID 27705909, 2016). "This work for the first time demonstrates the effectiveness of a combination of PARP1 inhibitor olaparib and alkylating agent DTIC for treating LIG4 deficient melanomas." (PMID 27705909, 2016). "Protein expression status of LIG4, RAD51, PARP1, Ku70 was determined by Western blot analysis in normal melanocytes and melanoma cell lines (DMBC11, DMBC12)." (PMID 27705909, 2016). "From the analysis, it seems that the invasive phenotype has greater downregulation in the D-NHEJ genes than proliferative, therefore selected melanomas with an invasive phenotype should display enhanced sensitivity to PARP1 inhibitors." (PMID 27705909, 2016). "We observed that PARP1 inhibitor olaparib sensitized melanomas with reduced expression of DNA ligase 4 (LIG4) to an alkylatimg agent dacarbazine (DTIC) treatment in vitro, while normal melanocytes remained intact." (PMID 27705909, 2016). "Alternatively, another important DNA-damage sensor and DDR regulator, known as PARP-1 (Poly-ADP-ribose polymerase 1), is also involved in the regulation of NF-kB in senescent melanoma cells undergoing the SASP." (PMID 25815006, 2015). "As a proof, PARP-1 inhibition in melanoma and cervical carcinoma lines enhanced in vitro sensitivity to temozolomide and promotes antitumor activity in ETS gene-rearranged PCa models." (PMID 25185441, 2014). "The fact that PARP1 and ATM genes are involved in cell repair, suggests that DNA repair signaling pathways are an important function in susceptibility to melanoma risk." (PMID 23537197, 2013). "In an in vitro model of melanoma, PARP-1 driven NFκB signaling led to an increase in the secretion of pro-metastatic cytokines during senescence, termed the PARP-1 NFκB-Associated Secretome, or PNAS." (PMID 24202328, 2013). "To determine the correlation between PARP-1 expression and disease progression in human melanoma, we used IHC to analyze the levels of vimentin, PARP-1, Snail1, E-cadherin and MITF in nodular and metastatic melanoma frozen biopsies." (PMID 23785295, 2013). "Results from human tissue arrays of melanoma suggest a complex interaction between PARP-1 expression and melanoma progression." (PMID 23785295, 2013). "(iv) Angiogenesis: the role of PARP-1 in promoting angiogenesis that fuels the growth of tumors can also be target of PARPi, because PARP-1 depletion or PARPi reduce vessel formation and expression of markers of angiogenesis in melanoma or endothelial cells." (PMID 24294592, 2013). "Our data showed that exposure to 11-dehydrosinulariolide results in cleavage of PARP-1 in A2058 melanoma cells in a time- and dose-dependent manner." (PMID 23015779, 2012). "Splenocytes from parp-1+/+ and parp-1-/- mice or G361 cells (a human melanoma cell line) were irradiated at 10 Gy." (PMID 17459151, 2007). "Consequently, elevated PARP1 expression is observed in various tumors, including melanomas, lung, and breast tumors." (PMID 39456202, 2024).
melanoma (continued). "After 24 h of HPF treatment, in all melanoma cell lines, immunoblots showed a decrease of bands representing full-length PARP1 expression and a correspondent increase of higher mobility band displaying cleaved-PARP1 level." (PMID 36674794, 2023). "To this aim, we investigated the mechanism of radioresistance conferred by c-Met in melanoma based on previous work indicating that some RTKs could activate PARP1 enzymatic activity by distinct mechanisms which are cancer dependent." (PMID 37215708, 2023). "Melanoma cells conserved high PARP-1 expression and activity under any IR dose." (PMID 37215708, 2023). "This indicates the possibility of an RT-mediated c-Met/PARP-1 interaction in melanoma." (PMID 37215708, 2023). "Firstly, we found that PARP-1 is highly expressed in melanoma cell lines." (PMID 37215708, 2023). "To address this question, we investigated the constitutive level of PARP-1 and its activity in different melanoma lines harboring various gene mutations under increasing doses of RT as it has not been reported yet in melanoma." (PMID 37215708, 2023). "Furthermore, this effect on melanoma cells treated with different inhibitors of the DDR was observed in other studies regarding targeted therapy using PARP1/2 and DNA-PK inhibitors." (PMID 36229655, 2023). "Furthermore, we added substantial proof for PARP-1 role in melanoma radioresistance by performing a KO of the gene, leading again to a significant radiosensitizing effect." (PMID 37215708, 2023). "PARP-1 inhibition by Olaparib or its KO mediates melanoma cell sensitivity to radiotherapy (RT)." (PMID 37215708, 2023). "Otherwise, PARP-1 mRNA expression levels presented as down-regulated in melanoma DPG-exposed cells." (PMID 35806253, 2022). "Mechanistically, PARP1 is associated with the stabilizing of HIF-1α, which plays a vital role in melanocyte transformation and represents an essential feature in malignant tumor growth, including melanoma." (PMID 36588679, 2022). "Moreover, in patients with elevated PARP1 expression, melanoma was more frequently located in the skin of the head and neck region (p = 0.015)." (PMID 33572647, 2021). "Little is known about the role of PARP1 in melanoma development and progression." (PMID 33572647, 2021). "These senescent cells develop a PARP-1 and NF-κB associated secretome (PNAS) containing chemokine CCL2 along with other SASP factors thereby augmenting the invasiveness of melanoma cells which might have escaped senescence." (PMID 33855023, 2021). "We aimed to investigate the prognostic significance of PARP1 expression in cutaneous melanoma through evaluation of mRNA and protein levels of PARP1 in normal melanocytes and melanoma cell lines, as well as in patients’ tissue material from surgical resections." (PMID 33572647, 2021). "Interestingly, PARP1 controls inflammatory cytokine transcription during senescence along with NFκB in melanoma cells." (PMID 32455851, 2020). "Since our studies indicated that 2HF could be useful in the therapy of melanoma when used alone and in combination with sunitinib or PARP1 inhibitors, we considered whether it could be used as systemic therapy as an adjunct to these drugs." (PMID 31615091, 2019). "In light of the potential for PARP1 inhibitors as therapeutics in melanoma, and the striking depletion of cellular PARP1 observed following 2HF treatment, we considered the possibility that 2HF could modulate the sensitivity of melanoma to PARP1 inhibitors." (PMID 31615091, 2019). "We conclude that 2HF–PLO gel may be useful for topical therapy of cutaneous metastases of melanoma and could enhance the antineoplastic effects of sunitinib and PARP1 inhibitors." (PMID 31615091, 2019). "Based on these results, melanoma cells were exposed for 24–48 h to 250–500 μM Ole and the level of apoptosis, assessed uisng western blotting of PARP1, confirmed that only 500 μM Ole was able to promote the expression of a significant level of cleaved PARP1 after 48 h of treatment." (PMID 30544808, 2018).
melanoma (continued). "The hazelnut extract, some neolignans, cedrusin and balanophonin and gallic acid are able to inhibit the growth of human cancer cells (primary melanoma, A375, metastatic melanoma, SK-Mel-28, and cervical cancer, HeLa) inducing apoptosis mediated by caspase-3 activation and PARP-1 cleavage." (PMID 28208804, 2017). "Thus, XPA knockdown sensitizes melanoma cells to cisplatin by impairment of autophagy through activation of PARP-1." (PMID 29112132, 2017). "We hypothesized that PARP1-dependent synthetic lethality could be induced in melanoma cells displaying downregulation of DSB repair genes." (PMID 27705909, 2016). "Indeed, when we performed sub-fractionation assays in three nervous system and two melanoma cell lines, we detected PARP1-DNA complexes in all (compare lanes 6 and 10)." (PMID 26505995, 2015). "A particular example is our use of the antibody for PARP-1 in a study of melanoma samples subjected to various treatment conditions, where the %CV between biological replicates decreased from 21% to 13%, enabling more reliable use in the study after normalization." (PMID 25501559, 2014). "PARP1 was studied previously in relation to melanoma; however, the rs3219090 was firstly detected in a GWAS study, and the validation of its protective role to MM predisposition has been confirmed in this study’s southern Mediterranean (Spanish) population (p-value 0.027)." (PMID 23537197, 2013). "Enzymatic inhibition, which decreases PARP-1 self PARylation, actually increases DNA binding and may be detrimental in some cancers, such as the malignant melanoma example given above." (PMID 24350055, 2013). "Hence PARP1 inhibition for overcoming invasive/resistant melanoma represents a novel prediction that could explain the previously observed context-dependent effects." (PMID 38183207, 2025). "Additionally, upregulation of PARP1 has been shown to increase melanoma cell proliferation." (PMID 38308491, 2024). "Indeed, the role of PARP1 in melanoma is dependent on MITF signaling." (PMID 35562405, 2022). "It is of interest that SK-MEL-24 was susceptible to this effect, implying that 2HF could also increase the effectiveness of PARP1 inhibitors in melanomas that are deficient in non-homologous end joining (NHEJ) DNA-repair." (PMID 31615091, 2019). "Likewise, it was observed that PMS treatment (1–10 μM, 24 h) induces pronounced PARP1-cleavage in A375R malignant melanoma cells even at low concentrations that do not cause this effect in A375 cells." (PMID 31035569, 2019). "Finally, we investigated if the drug combination could increase apoptosis in melanoma cells with respect to monotherapy by analyzing PARP1 cleavage (cPARP), which is a sensitive marker of cells undergoing apoptosis." (PMID 29423085, 2018). "It was found that polyphenolic compounds may mediate apoptosis by caspase activation and PARP1 cleavage; for example, Corylus avellana extract contains high amounts of polyphenols induces apoptosis in human malignant melanoma (SK-Mel-28) and human cervical cancer (HeLa) cell lines by this mechanism." (PMID 30171426, 2018). "In addition, analyses of the already existing databases strongly suggest that numerous melanomas could be sensitive to personalized medicine-guided PARP1 inhibitor-mediated synthetic lethality due to their putative deficiencies in DNA repair pathways." (PMID 27705909, 2016). "In addition, multiple melanoma samples displayed downregulation of at least one gene in HR pathway with higher frequency in the invasive phenotype suggesting their sensitivity to synthetic lethality triggered by PARP1 inhibitors." (PMID 27705909, 2016). "Targeting poly ADP-ribose polymerase 1 (PARP-1), a key DNA repair enzyme, with inhibitors like olaparib sensitizes melanoma cells to RT." (PMID 40867277, 2025).
melanoma (continued). "Compared to those in the control group, expression levels of full-length PARP1 and proliferative marker PCNA were significantly decreased in the LNT group, indicating the anti-proliferative and pro-apoptotic effects of LNT in melanoma." (PMID 39744474, 2025). "Other genes such as NR3C1, AXL, PARP1 and several HDAC genes were consistently found in invasive melanoma." (PMID 38183207, 2025). "The most consistent candidate drug treatments for invasive melanoma were glucocorticoid receptor (NR3C1) agonists, AXL inhibitors, PARP1 inhibitors and HDAC inhibitors, as target gene expression for drug families predicted to target invasive melanoma." (PMID 38183207, 2025). "We evaluated the benefit of PARP-1 and c-Met dual inhibition with RT in vivo in a melanoma xenograft model using the radioresistant HBL melanoma cell line." (PMID 37215708, 2023). "Proteolytic cleavage of PARP1, subG1 peak and the pan-caspase inhibitor z-VAD demonstrated the ability of IS20 and IS21 to induce apoptosis in leukemia, melanoma and NSCLC cells." (PMID 35265218, 2022). "The ability of IS20 and IS21 to affect cell viability, colony and sphere formation, to promote cleavage of PARP1, and to increase the expression of LC3B-II was also confirmed on A375 melanoma cell line." (PMID 35265218, 2022). "We found that the protein levels of PARP1 and PARP2 were higher in the melanoma cells compared to the healthy skin fibroblasts." (PMID 34073147, 2021). "In two normal human melanocyte cell cultures (HEMn-LP and HEMn-DP) and four melanoma cell lines (A375, WM1341D, Hs294T, and WM9), PARP1 protein localization was visualized using confocal microscopy." (PMID 33572647, 2021). "This analysis of such target genes expressed onto several cancer types reveals that only the increase in PARP1 and TYR expression is related to melanoma severity and survival." (PMID 34199192, 2021). "Blocking PARP-1, ATM, or NF-κB in melanoma cells prevents the secretion of chemokine CCL2 thereby restricting the deleterious pro-invasive properties of the inflammatory SASP mediated by PNAS." (PMID 33855023, 2021). "In the control groups of the four melanoma cell lines, ANST, ARPA, RERO and LIWE, the relative levels of PARP1 appeared to be higher than those of PARP2." (PMID 34073147, 2021). "To summarize, a combined treatment of PARP inhibitor and IR primarily resulted in a decrease or a constant level of PARP1 content, whereas the PARP2 content increased in all four melanoma cell lines." (PMID 34073147, 2021). "The baseline PARP1 and PARP2 levels were higher in the four melanoma cell lines ANST, ARPA, RERO and LIWE compared to the two healthy skin fibroblast cell cultures SBLF7 and SBLF9." (PMID 34073147, 2021). "We observed that the signal from PARP1 in normal melanocytes and the WM1341D melanoma cell line was weaker than the same signal in A375, Hs294T, and WM9 melanoma cells." (PMID 33572647, 2021). "Tumors with combined PARP1 and IDO1 high expression correlated with worse overall and melanoma-specific survival (p = 0.015, 0.0034 respectively)." (PMID 32380691, 2020). "In our study, we observed a strong correlation between high PARP1 and IDO1 expressions in mucosal melanomas." (PMID 32380691, 2020). "Accordingly, siRNA mediated silencing of HPSE expression in melanoma MDA‐MB‐435s cells led to significant increase in apoptosis, which was mediated by activation of caspase 3/PARP1 pathway." (PMID 31044520, 2019). "In order to obtain more direct evidence of apoptosis induced by the Les-3833 in human melanoma WM793 cells, the activation of caspase 3 and cleavage of the reparation enzyme PARP-1 were monitored by the Western-blot analysis." (PMID 28409496, 2017). "In addition, analysis of the TCGA and transcriptome microarray databases revealed numerous individual melanoma samples potentially displaying specific defects in DSB repair pathways, which may predispose them to synthetic lethality triggered by PARP1 inhibitor combined with a cytotoxic drug." (PMID 27705909, 2016).
melanoma (continued). "In the present study we showed that PARP1 inhibitor olaparib applied alone and in combination with DTIC (a drug used in melanoma treatment) was effective against melanoma cells displaying downregulation of LIG4 without affecting normal melanocytes." (PMID 27705909, 2016). "Currently, compound 86, namely E-7016 (PARP-1 IC50 = 0.04 μM), is under evaluation in combination with temozolomide in patients with advanced solid tumors or with wild-type BRAF stage IV or unresectable stage III melanoma." (PMID 40332429, 2025). "This analysis suggests several classes of drugs such as glucocorticoid receptor (NR3C1) agonists, AXL inhibitors, PARP1 inhibitors and HDAC inhibitors as the most consistently expressed candidate drug-treatments in invasive melanoma across all studies examined." (PMID 38183207, 2025). "To date, there are no reports regarding DTYMK and PARP1 inhibition on UM cell lines and their role in the progression of this rare subtype of human melanoma." (PMID 39195238, 2024). "While investigating the effects of reduced pH on the survival and metastasis of human melanoma cells, Peppicelli and others identified that cells possessing an anoikis resistant phenotype expressed high levels of EGFR, and reduced levels of cleaved PARP-1." (PMID 37181747, 2023). "Accordingly, we hypothesized that co-targeting DNA repair (PARP-1) and relevant activated RTKs, c-Met in particular, may radiosensitize wild-type B-Raf Proto-Oncogene, Serine/Threonine Kinase (WTBRAF) melanomas where RTKs are often upregulated." (PMID 37215708, 2023). "In our model, melanoma cells showed a degradation band (approximately 62 kDa) of cleaved PARP-1 when incubated with 0.15 mM Rb4 for 16 h and 18 h but not for 2, 4 or 6 h." (PMID 35190586, 2022). "The role of PARP-1 in promoting angiogenesis that fuels the growth of tumors, can also be a target of PARPi, because the PARP-1 depletion or PARPi reduce the vessel formation and the expression of the markers of angiogenesis in melanoma or endothelial cells." (PMID 36555812, 2022). "Thus, our results indicate that, at least in part, both PARP-1 and MMP-9 are inhibited by DPG action, leading to abolishing melanoma cell migration." (PMID 35806253, 2022). "The increased level of cleaved Poly (ADP-ribose) polymerase (PARP1) indicates that apoptosis may contribute to cell death after silencing of ILK at least in WM793 and early-stage melanoma cells." (PMID 33916175, 2021). "Enhanced PARP1 immunoreactivity in melanoma cells in the whole group of patients (with and without lymph node metastases) was significantly correlated with a high mitotic index and the presence of ulceration (p = 0.001 and p = 0.036, respectively)." (PMID 33572647, 2021). "Therefore, thanks to this cross-validation among different databases, MAOA, PARP1 and TYR represent the best CMT with significant differential expression in melanoma vs. control biopsies." (PMID 34199192, 2021). "Chemotherapeutic drugs or oxidative stress induced DNA damage engage PARP-1/ATM/NF-κB signaling cascade to induce senescence in melanoma and non-melanoma cells." (PMID 33855023, 2021). "In our studies, we found hints for correlations between PARP1 content and sensitivity to PARPi: among the melanoma cell lines tested, ANST had the lowest relative PARP1 level as well as the lowest sensitivity against both inhibitors in the colony formation experiments." (PMID 34073147, 2021). "By linear regression analyses, increased number of mitoses measured per 1 mm2 was correlated with overexpression of PARP1 in nuclei of mucosal melanoma cells (p = 0.0052) but not to IDO1 or PD-L1 expression." (PMID 32380691, 2020). "Due to the significant correlation between high PARP1 expression, poor prognosis, and enhanced mitotic activity, potential inhibition of PAPR1 in mucosal melanoma patients could be beneficial." (PMID 32380691, 2020).